CD47 (CD47 molecule)
Diseases named in the same sentence as CD47 in open-access papers (continued):
Sharing a sentence is not in itself a finding about the gene and the disease.
tumor (continued). "Expressions of CD90, EpCAM, CD133, CD24, SOX9, CD44, CK19, and CD47 were positively related to immune infiltration level in HCC, negatively related to tumor purity." (PMID 32184801, 2020). "constructed tumor microenvironment‐activatable prodrug vesicles combined with αCD47 that prevented tumor metastasis and recurrence by ICD and CD47 blockade." (PMID 33304763, 2020). "CD47-targeted NIR-PIT increases direct cancer cell death and phagocytosis, resulting in inhibited tumor growth and improved survival in a model of human bladder cancer." (PMID 32746880, 2020). "Furthermore, the abundant expression of CD47 throughout the entire human body could eventually lead to the formation of “Ag sinks” that would prevent anti-CD47 antibodies from reaching the targeted tumor." (PMID 32457743, 2020). "Intriguingly, the super-enhancer of CD47, also known as the “don’t eat me signal”, was likely switched on during OC3 tumor formation, since a significant difference of CD47 expression between the OC3 and TW2.6 tumors was noticed." (PMID 32605311, 2020). "Again, these findings support active crosstalk between CD47 and HER2 in a radiation-treated tumor microenvironment." (PMID 32929084, 2020). "In this study, we uncovered a novel mechanism of promotion of anti-tumor immunity by miR-128 through regulating the ZEB1/CD47 axis, thus linking an EMT regulatory program to anti-tumor immunity in PDAC." (PMID 32536914, 2020). "CD47 plays a role in blocking phagocytosis, improving tumor survival, metastasis, and angiogenesis: CD47-CAR-T cells are expected to kill cells with high expression of CD47 and to be a potential treatment for SCLC." (PMID 32899891, 2020). "By combining CD47-SIRPα disruption with IgA antibodies against HER2, one group was able to enhance tumor cell opsonization and decrease tumor burden via neutrophil trogocytosis, a method of acquiring target cell plasma membrane fragments." (PMID 35582455, 2020). "In this study, we show that in addition to tumor cells, the majority of tumoral and paratumoral NK cells and CD8+ T cells also express CD47, and the levels of its expression are even higher than in the parallel nonlymphocyte cells." (PMID 32811852, 2020). "Immunohistochemistry was employed to identify the characteristics of CD47 and CD133 in 26 pairs of tumor tissues and adjacent non‐tumor tissues and 136 ESCC tissues." (PMID 30741466, 2019). "To understand the relationship among CD47, PD-L1, and TAM in PDAC, we stained the tumor specimen from 106 PDAC patients with anti-CD47, anti-PD-L1, anti-CD68, and anti-CD163 antibodies." (PMID 31771616, 2019). "In the MPC-83 tumor model, combination treatment increased the proportion of PD-1+CD8+ T lymphocytes in spleens and tumors compared to either anti-CD47 or anti-PD-L1 alone." (PMID 31771616, 2019). "First, the expression of CD47 and macrophage markers was analyzed in FFPE thyroid tissues from tumor-bearing Thyro-DT mice." (PMID 30938231, 2019). "Through coordination blockade the expression of CD47 and CD274 in tumor, the immune system can maintain the high quality of T cells and NK cells in vivo and prevent the immune escape of CTCs." (PMID 30872703, 2019). "In the CD47 knockdown group, 1 × 105 MDA‐MB‐231.SC cells formed tumour xenografts in nude mice with 80% efficiency, while the efficiency in the NC group is 100%." (PMID 31273952, 2019). "The function modifying CD47 antibody B6H12 has been used extensively as an antagonist of CD47 signaling through SIRPα in preclinical studies and demonstrated tumor suppressing activities in many xenograft models." (PMID 31632920, 2019). "In vitro flow cytometry data proved that CD47 and CD274 were overexpressed on the tested mouse tumor cell lines." (PMID 30872703, 2019). "Using immunohistochemistry, we examined tumor-infiltrating CD68+ pan-macrophages (CD68+ M) and CD163+ M2 macrophages (CD163+ M2) and tumor expression of CD47 and PD-L1 proteins in 106 cases of PDAC." (PMID 31771616, 2019).
tumor (continued). "The variables of CD47 expression, CD68+ M or CD163+ M2, tumor diameter, N stage, and grade were included in the multivariate analysis." (PMID 31771616, 2019). "To examine the effect of anti-CD47 mAb on PDAC, we used the tumors from two patients with PDAC (P962 and P989) to create tumor implantations in nude mice and in NCG mice." (PMID 31771616, 2019). "The simultaneous blockade on both CD47 and CD274 checkpoints inhibited tumor growth and CTCs metastasis more potently than a single antibody inhibition or blank control on 4T1 tumor mouse model in vivo." (PMID 30872703, 2019). "We also performed a combined analysis of the CD47 and IDO1 tumour cell intensities using three-tiered classification; high intensity of both markers, high intensity of only one marker, low intensity of both markers." (PMID 31358801, 2019). "The tumour samples were stained for inducible nitric oxide synthase (iNOS, M1 marker), CD163 (M2 marker), FoxP3 (Treg marker), CD47 and IDO1." (PMID 31358801, 2019). "CD47 blockade promotes antibody-dependent cellular phagocytosis (ADCP) of tumor cells by macrophages and tumor killing by cytotoxic T lymphocytes." (PMID 31921125, 2019). "Anti-CD47 antibody treatment of ATC xenotransplanted mice increased the frequency of TAMs, enhanced the expression of macrophage activation markers, augmented tumor cell phagocytosis, and suppressed tumor growth." (PMID 30938231, 2019). "Results conclude that CD47 and CD133 expression is increased in tumor tissues as compared to adjacent non‐tumor tissues." (PMID 30741466, 2019). "Further analysis revealed that the combination treatment increased the proportion of PD-1+CD8+ T cells in the peripheral blood, when compared to either anti-CD47 or anti-PD-L1 alone in both Panc02 and MPC-83 tumor-bearing mouse models." (PMID 31771616, 2019). "Also, the relationship between the tumor expression of CD47 and TAM in PDAC remains unclear." (PMID 31771616, 2019). "Surprisingly, anti-CD47 treatment had a limited anti-tumor effect in PDX models, though tumor-bearing nude mice showed less tumor burden when treated with anti-CD47." (PMID 31771616, 2019). "Although further mechanistic studies are still required for collation, our data presented—through combining CD47 and CD133 expression—the tumor stemness index as an independent prognostic factor for both OS and PFS." (PMID 30741466, 2019). "After TNF-α/NF-κB1 being successfully abrogated by BAY 11–7082, anti-angiogenic treatment-induced CD47 upregulation was diminished in NSCLC tumors and produced increased anti-tumor effect." (PMID 31829270, 2019). "To understand the role of CD8+ T lymphocytes following targeting of both CD47 and PD-L1, we examined the proportion of PD-1+CD8+ T cells from lymphocytes isolated from the peripheral blood, spleen, and tumor tissue, respectively, using flow cytometry." (PMID 31771616, 2019). "The tumor volume for CD-47-siRNA-LPH-NPs was found to be smaller than the control group, with approximately 93% reduction of tumor volume in comparison to the untreated group." (PMID 29861465, 2018). "Dual downregulation of CD47 and SIRPα by RRx- 001 results in TAM repolarization and phagocytosis of tumor cells." (PMID 30400835, 2018). "Comparison of CD47 occupancy at 10 and 30 mg/kg demonstrated that greater levels of ALX148 are required to attain full occupancy in the tumor than are required for the periphery." (PMID 30133535, 2018). "Functional studies showed that restoration of miR-708 expression in the T-ALL cell line is sufficient to promote phagocytosis by macrophages in the absence or presence of the anti-CD47 antibody to eradicate T-ALL cells, and inhibited tumor engraftment in vivo." (PMID 29368647, 2018). "As the only commercially available CD47-antibody able to induce cell death in solution, CC2C6 should enable further studies that enhance understanding of a 'don’t eat me' tumour cell antigen that can be exploited to turn on itself." (PMID 29748606, 2018).
tumor (continued). "The ImmunoINTEL panels were complemented with drop-in IMR and IMR-L markers (PD1/PDL1, TIGIT/CD112-CD155, TIM-3/Galectin-9, SIRPa/CD47, LAG-3/HLADR) to profile the functional status of TILs, and to study the cytotoxic potential of tumor TILs." (PMID 30400835, 2018). "CD47 targeting biAbs, tethered to cancer cells by their TAA binding arm, remodel the tumor microenvironment enhancing macrophage tumoricidal function." (PMID 30400822, 2018). "The roles of CD47-targeting monotherapy might be problematic due to the significant side effect of causing red blood cell destruction and lack of preference of targeting tumor-infiltrating macrophages." (PMID 30577797, 2018). "Given the established effect of CD47 blockade on macrophage activity, we examined the effect of ALX148 on myeloid cells within the tumor microenvironment." (PMID 30133535, 2018). "All cultures were characterized for tumor surface or stem-like marker expression, namely CD46, CD47, CD55, CD56, CD63, CD90, and CD99." (PMID 28545562, 2017). "Fucosylated glycans, Lewis Y (Ley), can enhance the capacity of CD47-SIRP signaling and then enables the tumor cell to evade the phagocytosis or programmed cell clearance." (PMID 28977844, 2017). "CD47 is also known as a “don’t eat me signal” through binding to SIRP-α (signaling regulatory protein alpha) and blocking phagocytosis of tumor cells mediated by SIRP." (PMID 29065481, 2017). "A CD47 × CD20 antibody, which demonstrated tumor-selective binding, served as proof of concept for this approach." (PMID 28234345, 2017). "To go one step further in our study, we are now proposing to optimize the CRISPR-Cas9 genome editing technology to knock-out CD47, PNPLA2 and ATP5B in tumor and macrophage cells." (PMID 28403150, 2017). "While the combination of PNPLA2 inhibitors and Angiostatin was toxic and did not allow us to analyze their combined effects on macrophage differentiation and phagocytosis, we investigated the relative role of CD47 and ATP5B in tumor cell phagocytosis." (PMID 28403150, 2017). "The turning off of this ‘switch' resulted in a 70% reduction of CD47 levels, which promoted phagocytosis of MCF7 cancer cells in vitro and reduced tumour size in xenotransplantation models." (PMID 28378740, 2017). "We have previously shown that the CD47-blocking agent TTI-621 triggers tumor cell phagocytosis by M(IFN-γ) macrophages in vitro and exhibits anti-tumor activity in vivo." (PMID 29084248, 2017). "More remarkably, our findings suggest that the knockdown of CD47 significantly reduced cell migration in vitro, and inhibited NSCLC tumor growth and metastasis in vivo." (PMID 27411490, 2016). "To detect the baseline antibody-mediated cellular cytotoxicity, we performed an additional comparison of tumor cells (GBM6) and macrophages (M0) pretreated with anti-CD47 or isotype-matched antibody (mouse IgG4) before coincubation." (PMID 27092773, 2016). "It plays a functional role in inhibiting tumor growth, cell migration, and neovascularization; it also acts as an endogenous tumor suppressor by interacting with its receptors, CD36 and CD47, or activating transforming growth factor-beta signaling." (PMID 27513329, 2016). "In summary, we revealed that CD47 is overexpressed in NSCLC, and that it is correlated with advanced tumor progression and more aggressive metastasis." (PMID 27411490, 2016). "One tumor cell line, GBM4, had a particularly high CD47 expression and displayed a lower baseline and antibody induced phagocytosis." (PMID 27092773, 2016). "In this study, we provided novel evidence for the overexpression of CD47, as well as its biological significance and functional consequence in NSCLC, using both human tumor tissues and cancer cell lines." (PMID 27411490, 2016). "Blockade of this signal via anti-CD47 antibody in primary human xenotransplant mouse models of DLBCL and FL showed both significant reduction of tumor burden and increased survival." (PMID 25941795, 2015).
tumor (continued). "On the one hand, antibodies targeting CD47 or SIRPα, recombinant SIRPα, or TSP1-derived proteins promote phagocytosis and tumor cell elimination by disrupting the CD47–SIRPα interaction and/or inducing Fc-dependent mechanisms or PCD." (PMID 25734483, 2015). "On the other hand, the binding of CD47 to 4N1K, a decapeptide derived from the TSP1 C-terminal domain, kills tumor cells and inhibits tumor growth in vivo." (PMID 25734483, 2015). "A number of anticancer approaches attempting to kill tumor cells by phagocytosis, antibody-dependent cell-mediated cytotoxicity, or PCD have relied on CD47 targeting by specific mAbs." (PMID 25734483, 2015). "The cell-surface protein CD47, together with CD44 and ALDH2, that were found up regulated at gene level in the CSCs subset, were also overexpressed in a high fraction of tumor cells." (PMID 26452033, 2015). "Given that TAMs are present in large numbers within tumors, it's possible that anti-CD47 antibody therapy has the potential to restore TAM immunosurveillance and fundamentally alter the role of macrophages in tumor biology." (PMID 26093091, 2015). "Indeed, TSP-1/CD36/CD47 trimolecular signaling platform dynamics as well as interactions involving co-receptors and soluble ligands exert pleiotropic activities on cancer progression, by directly modulating cancer cells behavior or by acting on tumor microenvironment stromal cells." (PMID 26578962, 2015). "The results suggest that CD44, CD47 and c-met participate in the development of the malignant biological behavior of OCCC and promote tumor progression and poor prognosis." (PMID 25658794, 2015). "Moreover, recent data pointed out that CD47 mRNA expression in patients are correlated with decreased survival in several cancer types and antibody blockade of CD47 yielded promising results in mice bearing human xenografts reducing tumor growth as well as metastasis." (PMID 26046793, 2015). "We have previously shown that luminal-type circulating tumor cells (CTCs) co-expressing the tyrosine-kinase MET and CD47, a ligand involved in cancer cell evasion from macrophage scavenging, are able to initiate metastasis in xenografts." (PMID 25230070, 2014). "The majority of GFP+ tumor cells expressed CD48 (99.3±0.7%), CD47 (89.5±6.9%) and Mac1 (74.4±14.7%), while expression of Gr1 (4.73±2.65%), B220 (1.35±1.52%), CD4 (18.6±16.8%), and Ter119 (3.13±1.6%) was low or absent." (PMID 22952867, 2012). "In the absence of treatment, tumor growth was comparable among all three groups, indicating that neither CD47 nor DNAJC13 knockout alone significantly suppresses tumor progression in vivo." (PMID 41601654, 2026). "Here, we integrated single cell RNA sequencing and proteomic analysis to identify that insulin-like growth factor binding protein 2 (IGFBP2) was co-expressed with CD47 in hypoxic mesenchymal-like GBM subpopulations, synergistically promoting tumor progression and immune evasion." (PMID 41620401, 2026). "Genetic and pharmacologic perturbations revealed that microglial phenotypes could be shifted by inhibiting TGFβ signaling or by deleting the tumor cell surface antigens CD24 and CD47." (PMID 41369553, 2026). "Among these, CD47, a critical self-protective "don't eat me" immune checkpoint against macrophage immunosurveillance, is frequently upregulated in TNBC, contributing to tumor immune evasion." (PMID 42007362, 2026). "When combined with anti-CD47 therapy, the formulation achieved synergistic tumor suppression (up to 70.3%) without systemic toxicity." (PMID 41510171, 2026). "In this study, the results showed that up-regulation of STAT3 and CD47 helped tumour cells escape phagocytosis by macrophages, and GMI could participate in the inhibition of the STAT3-CD47 signalling axis." (PMID 41438583, 2026). "Tumors lacking DNAJC13 exhibited enhanced sensitivity to CD47 blockade, with significantly reduced tumor volume compared to control tumors treated with antibody." (PMID 41601654, 2026).
tumor (continued). "For CD47 CPS, there was a significant difference in NAC between the high- and low-expression groups (P = 0.011), and for CD47 TPS, significant differences were observed in clinical tumor stage (T) and NAC between the high- and low-expression groups (P = 0.046 and 0.049, respectively)." (PMID 40926176, 2026). "Additionally, blockade of the CD47–signal regulatory protein (SIRP)α axis is an emerging approach that enhances macrophage‐mediated phagocytosis and promotes tumor cell clearance." (PMID 41426206, 2026). "Moreover, we identified CD47, an innate immune checkpoint molecule expressed on tumor cells, as the downstream molecule of SMYD3 that inhibits anti‐tumor immunity in ccRCC." (PMID 40548645, 2025). "A small dose of SIRPα antibody is sufficient to block the CD47-SIRPα pathway in tumor cells without leading to erythrocyte destruction or other hematological adverse effects." (PMID 40356928, 2025). "OC47‐Ce6 can simultaneously bind to CD47 on tumor cells and TLRs on TAMs, promoting TAM polarization to the M1 state and blocking the “don't eat me” signal on tumor cells, thereby stimulating TAMs to phagocytose tumor cells effectively." (PMID 40287972, 2025). "Overall, the combination of NDV with CD47 blockade reduced the intratumoral level of CD47 but did not increase tumor antigen phagocytosis by APCs or the proliferation of effector CD8 T cells." (PMID 41322194, 2025). "Therefore, our findings highlight miR-96-5p as a crucial tumor suppressor in the progression of PDAC, with biological, mechanistic and clinical effects on human PDAC and the CD47/SIRPα signaling pathway." (PMID 41350707, 2025). "While CD47 overexpression prolongs NK cells’ persistence, its potential to mimic tumor immune evasion should not be overlooked." (PMID 40723807, 2025). "oAd-CD47 effectively inhibited the growth of CT26, B16, and ID8 tumor cells." (PMID 40814015, 2025). "Notably, APM mitigates tumor immunosuppression triggered by PTT through AC, suppressing the COX-2/PGE2 pathway and immune evasion signal CD47." (PMID 40040956, 2025). "Specifically, S-nitrosylation appears to modulate CD47 internalization via its interaction with CXCR4, suggesting that nitric oxide-dependent post-translational modifications influence the balance between tumor cell survival and immune clearance." (PMID 40563669, 2025). "Additionally, CD47 can activate angiogenic factors such as VEGF, promoting tumor blood vessel formation, which supplies essential nutrients and oxygen for tumor growth and metastasis." (PMID 39781344, 2025). "In addition to this mechanism, CD47 overexpression blocks macrophage phagocytosis, checkpoint deletions (PD-1, TIGIT) prevent tumor-mediated suppression, and CISH knockout boosts cytokine signaling and persistence in the tumor microenvironment." (PMID 41487532, 2025). "Binds to CD47 and upregulates CRT expression to promote endocytosis and metabolism of tumor cells." (PMID 40657202, 2025). "Administration of oAd-CD47 alone did not significantly induce a neoantigen-specific T cell response in tumor-bearing mice." (PMID 40814015, 2025). "Furthermore, because of the innate tumor-homing ability of nanovesicles and the specificity of the RS17 peptide to bind CD47, they displayed good tumor-targeting properties." (PMID 40051791, 2025). "Collectively, these findings expand the functional landscape of CD47 beyond immune evasion and suggest that CD47 may also contribute to CRC progression through metabolic reprogramming and tumor-intrinsic signaling pathways." (PMID 41514569, 2025). "Tumor cells evade phagocytosis by overexpressing CD47, which engages SIRPα on macrophages to transmit a "do not eat me" signal." (PMID 41417432, 2025).